IL1B (interleukin 1 beta)
Diseases named in the same sentence as IL1B in open-access papers (continued):
Sharing a sentence is not in itself a finding about the gene and the disease.
myocardial ischemia (continued). "It has been reported that hearts from TLR4-defctive mice and TLR4 knockout mice display attenuated NF-κB activation and reduced production of pro-inflammatory cytokine (TNF-α, IL-1β and IL-6) following myocardial ischemia with a short period of reperfusion." (PMID 25823011, 2015). "Similarly, IL-1β levels are elevated during myocardial ischemia, contributing to the activation of myofibroblasts, which are implicated in cardiac remodelling and the impairment of systolic function post acute MI." (PMID 40076654, 2025). "Moreover, increased LxA4, VEGF and IL-1β levels were observed in patients with reduced myocardial ischemia after treatment." (PMID 36910537, 2023). "The GXDSF significantly reduced myocardial ischemia area, reduced myocardial structural injury, decreased the levels of interleukin (IL-1β, IL-6) in serum, decreased the activity of myocardial enzymes, increased the activity of superoxide dismutase (SOD), and reduced glutathione in rats with MIRI." (PMID 37098925, 2023). "In addition, NLRP3, caspase-1 cleavage, and particularly IL-1β were induced early during myocardial ischemia/infarction." (PMID 34752417, 2022). "Kyn may act as a signaling molecule to activate the Sirt3-acSOD2/IL1β pathway leaded to macrophage cells inflammation and oxidative stress after myocardial ischemia injury." (PMID 36405744, 2022). "Kyn could induce macrophage cells inflammation and oxidative stress by activating the Sirt3-acSOD2/IL-1β pathway following myocardial ischemia injury." (PMID 36405744, 2022). "Furthermore, valsartan has been shown to inhibit cardiac TNF-α, IL-6, and IL1β production in a rat model of myocardial ischemia." (PMID 35163209, 2022). "Additionally, in isoprenaline-induced rats, Granule of BU-XIN RUAN-MAI ameliorated myocardial ischemia by downregulating the inflammatory factor levels of IL-6, IL-1β, and TNF-α." (PMID 31949464, 2019). "Myocardial ischemia/reperfusion can cause cytokines such as TNF-α, IL-6, and IL-1β." (PMID 31249649, 2019). "The potential mechanisms might be associated with down-regulated expression of TGF-β1, TNF-α, IL-1β, ASK1, NF-κB Bax, up-regulated expression of Bcl-2 and Gata4, activation of eNOS pathway to ameliorate myocardial ischemia, and enhanced cardiac repair." (PMID 24260217, 2013). "Since IL-1β and other proinflammatory cytokines may also be actively involved in the regulation of matrix remodeling processes after myocardial ischemia, the issue of tissue remodeling and the regulatory effect of IL-1β on MMP activity could be very important." (PMID 22011328, 2011). "Since IL-1β and other pro-inflammatory cytokines may also be actively involved in the regulation of matrix remodeling processes after myocardial ischemia, the issue of tissue remodeling and the regulatory effect of IL-1β on MMPs activity could be of outstanding importance." (PMID 19855846, 2009). "Our findings showed that patients with a history of myocardial ischemia showed high expression of IMA, H-FABP, and the inflammatory factors IL-1β, TNF-α, and IL-6." (PMID 40236258, 2025). "Among them, TNF and IL can inhibit the release of inflammatory cytokines TNF-α and IL-1β, and reduce myocardial cell apoptosis and other damage through SOD-mediated inhibition of oxidative stress, thereby improving myocardial ischemia-reperfusion injury." (PMID 40574818, 2025). "Strong stimulation, such as myocardial ischemia, activates myocardial cells and releases cytotoxic mediators such as IL-6, TNF-α, and IL-1β." (PMID 40298805, 2025). "Myocardial ischemia–reperfusion induces ROS synthesis, triggering the release of proinflammatory factors (such as TNF-α, IL-6, IL-1β)." (PMID 38541636, 2024). "During acute myocardial ischemia, NLRP3 is activated both in circulating inflammatory cells and in cardiomyocytes, contributing to interleukin (IL)-1β and caspase-1 release, respectively." (PMID 35406729, 2022).
myocardial ischemia (continued). "Compared with the sham operation group, the myocardial ischemia-reperfusion injury group showed significant increases in TLR4, NF-KB, IL-1β, TNF-α, and IL-6." (PMID 34093716, 2021). "Results showed that myocardial ischemia resulted in significant increases in the levels of LDH, cTn and IL-1β." (PMID 31816891, 2019). "Alterations of lipid profile, cardiac and inflammatory markers (Il-1β, PTX 3 and TNF- α) were observed in myocardial ischemia group." (PMID 23036047, 2012). "In myocardial ischemia/reperfusion infarction, the cross signaling between Axl and TLR4 in cardiac macrophages directed a switch from glycolysis to lipid metabolism and the secretion of proinflammatory IL-1β." (PMID 39684449, 2024). "HMGB1 is up-regulated in a myocardial ischemia–reperfusion injury model, which increases the expression level of phosphorylated NF-κB p65, activates the NLRP3 inflammasome and induces the release of mature IL-1β." (PMID 35865525, 2022). "In an animal model of myocardial ischemia, the expression of EGFR in alveolar macrophages was up-regulated, and contributed to the expression of proinflammatory cytokines (such as TNF, IL-6, IL-1β), chemokines (such CXCL2/MIP-2, MCP-1, and CCL3) and iNOS." (PMID 35095926, 2021). "The underlying mechanisms may be via the down-regulation of TNF-α, TGF-β1, IL-1β, Bax, and the up-regulation of Bcl-2, VEGF, Akt and eNOS expression to attenuate myocardial ischemia, enhance neovascularization and cardiac repair." (PMID 31792327, 2019). "The activation of NF-κB following myocardial ischemia could induce the production of TNF-α by myocardial tissues in addition to regulating the expression of numerous genes, including IL-1β, IL-6, ICAM-l and VCAM-1." (PMID 25667680, 2015). "This led us to the conclusion that the regulation of myocardial cytokines differs from the regulation of serum cytokines, and that at least TNF and IL-1β are not primarily regulated through TLR4 in myocardial ischemia/reperfusion." (PMID 17592640, 2007).
cervical carcinoma (60 papers, 2011 to 2026). A carcinoma arising from either the exocervical squamous epithelium or the endocervical glandular epithelium. "IL-1β is associated with tumorigenesis, angiogenesis, metastasis, and an increased risk of progression to cervical carcinoma in women with cHSIL." (PMID 40362199, 2025). "The results revealed that low expression of LAG3 was linked to a poor prognosis in cervical cancer (p = 0.0027), while high expression of IL‐1β was also associated with poor prognosis (p = 0.0014)." (PMID 41025546, 2025). "Quantitative analysis of IL-1β in cervical cancer tissue by qPCR indicated that women with low levels of IL-1β were at higher risk." (PMID 40244135, 2025). "Other molecular mediators associated with cell proliferation are the cytokines IL-1β and IL-8, which are excessively secreted in cervical cancer and contribute to metastasis, angiogenesis, and cell survival." (PMID 36678600, 2023). "Some research argued that IL1A and IL1B were associated with tumor progression and prognosis; in addition, IL-1A was an independent predictor of survival in cervical cancer patients." (PMID 36253777, 2022). "IL1B-511T carriers present a higher risk of developing cervical cancer, acute myeloid leukemia, or chronic myeloid leukemia." (PMID 32635472, 2020). "Rs16944 AA genotype of the IL‐1B gene was found to be significantly associated with higher cervical cancer risk (OR = 2.16, p = 0.028) in the Egyptian population." (PMID 31222982, 2019). "Our result revealed IL‐1B rs1143627‐AA (OR = 1.98, p = 0.029) and rs16944‐GG (OR = 2.01, p = 0.025) was associated with an increased risk of cervical cancer." (PMID 31222982, 2019). "Rs3136558 polymorphism of IL‐1B in the co‐dominant and dominant models showed that IL1B rs3136558 GA heterozygotes had a decreased risk of cervical cancer." (PMID 31222982, 2019). "Our study provides accumulating evidence for the association between IL‐1B gene polymorphism and the susceptibility of cervical cancer." (PMID 31222982, 2019). "Some authors attribute the rise in IL-1β plasma to an increased risk of cervical cancer in women with polymorphisms." (PMID 31554368, 2019). "We aimed to evaluate the contribution of IL‐1B polymorphisms to the susceptibility of cervical cancer in Chinese Uygur population." (PMID 31222982, 2019). "Survival curves were plotted for 391 cervical cancer cases and the result found that the high expression level of IL‐1B significantly increased the death risk of cervical cancer (p = 0.0014)." (PMID 31222982, 2019). "Subsequently, haplotype analysis was used to explore the association of IL‐1B polymorphisms with cervical cancer susceptibility." (PMID 31222982, 2019). "In conclusion, this is an exploratory study to examine putatively functional genetic variants of the IL‐1B gene with cervical cancer risk in Chinese Uygur population." (PMID 31222982, 2019). "For the first time, our results provide evidence on polymorphism of IL‐1B gene associated with cervical cancer risk in Chinese Uygur population." (PMID 31222982, 2019). "Similar, persistent HPV16/18 infection in Indian population with the A‐allele (rs16944) of IL‐1B is associated with development of cervical carcinoma." (PMID 31222982, 2019). "With respect to cervical cancer, studies have revealed that the positive association with increased IL‐1β secretion and cervical cancer risk (Magdy A. Al‐Tahhan, Etewa, & Behery, 2011)." (PMID 31222982, 2019). "We observed that loss of IL-1β production in cervical cancer cells led to a loss of paracrine IL-8 transcription." (PMID 30089163, 2018). "In cancer studies, IL-1β is associated with a poor prognosis, and in cervical cancer research, it supports tumor progression and carcinogenesis." (PMID 29854832, 2018). "Recent studies have shown that IL-1β is associated with development of cervical carcinoma with persistent HPV16/18 infection." (PMID 28402258, 2017).
cervical carcinoma (continued). "Several case-control studies have been conducted to determine the roles of IL-1B promoter single nucleotide polymorphisms (SNPs) in the development of cervical cancer, especially for C-511T (rs16944)." (PMID 23554684, 2011). "The IL-1B-511T and -31C alleles have been found to confer an increased risk for the development of cervical cancer, especially among subjects having higher levels of IL-1β." (PMID 23554684, 2011). "Moreover, the rs1143630 T allele has been identified as exerting a protective effect against cervical cancer susceptibility, possibly attributable to the reduced pro‐inflammatory nature of IL‐1β, which reduces tumor invasion." (PMID 37937732, 2024). "Expression of IL-1β in the cervical cancer group was observably lower compared with that in the normal control group and low-grade squamous intraepithelial lesion group, and women with low IL-1β expression had a higher risk of precancerous lesions progressing to cancer." (PMID 36497244, 2022). "Similarly, the quantification of IL1B mRNA by qPCR in cervical cancer biopsies showed an increase in the risk of progression of pre-neoplasic lesions in women with lower IL1B expression." (PMID 32635472, 2020). "However, among the notable findings in our study was the observation that IL‐1B rs16944‐G was associated with increased risk of cervical cancer, which is inconsistent with previous results." (PMID 31222982, 2019). "Furthermore, multiple genetic models (dominant, recessive, additive, and co‐dominant models) were applied for analyzing the association between the SNPs in the IL‐1B gene and cervical cancer risk by unconditional logistic regression analysis adjusted for age." (PMID 31222982, 2019). "Besides, UALCAN database assessed the association between the expression of IL‐1B gene and the prognosis of cervical cancer." (PMID 31222982, 2019). "Therefore, a Case–Control study was carried out to evaluate the possible correlation of IL‐1B polymorphisms with the risk of cervical cancer among Chinese Uygur population." (PMID 31222982, 2019). "Furthermore, IL-1β down regulation in HPV induced carcinogenesis is underlined by the fact that specific polymorphisms in IL-1β have been demonstrated to be associated with cervical carcinoma risk." (PMID 30089163, 2018). "The same loss of pro-IL-1β was observed in cervical cancer cell lines positive for HPV16." (PMID 30089163, 2018). "Based on our findings we hypothesized that loss of IRF6 and IL-1β expression favours cervical cancer development." (PMID 30089163, 2018). "Our previous study revealed that the mean plasma IL-1β levels in cervical cancer cases were significantly higher than those in controls (P = 0.0002), and plasma IL-1β levels above the 75% quartiles in controls were associated with a 1.74-fold significant increase in the risk of cervical cancer." (PMID 23554684, 2011). "While its overexpression promotes inflammation, tumor invasion, and metastasis, certain genetic polymorphisms in the IL1B gene (e.g., rs1143627, rs16944) have been linked to increased risk of cervical cancer, whereas others (rs3136558, rs1143630) may exert protective effects." (PMID 41267807, 2025). "Two studies among Indian populations showed association of genetic variation at this site with cervical carcinoma risk, with allele 2 bearing the strongest association with increased cancer risk, both in single genotype analysis and in haplotype analysis with the IL1B gene." (PMID 28280748, 2017). "Studies have found that the molecular typing of pyroptostic‐related genes (PRGs) in cervical cancer can predict prognosis, and the GNAZ/LAG3/IL1B/CA2/SPRR3 risk scoring model has been constructed." (PMID 41025546, 2025). "This study found that CD200Fc inhibits LPS-induced NLRP3 inflammasome activation and release of IL-1β in SiHa and Caski human cervical cancer cells." (PMID 39769450, 2024).
cervical carcinoma (continued). "constructed a new prognosis predication model based on 8 risk-related PRGs (GPX4, GSDME, GZMA, GZMB, IL1B, NOD1, PRKACA, and TNF) in cervical cancer, which had good predictive ability (AUC = 0.794)." (PMID 35912258, 2022). "As the cervical cancer cells present an overexpression of IL-1β, then the NF-κB pathway will be highly activated by IL-1RAP." (PMID 36499246, 2022). "Studies have shown that the level of IL1B in plasma of patients with cervical cancer was significantly higher than that of the control group, and the expression level of IL1B played an important role in the carcinogenesis of cervical cancer." (PMID 34975504, 2021). "Previously, IL1B rs1143643 was related to various diseases, such as neonatal sepsis, pediatric asthma, and cervical cancer." (PMID 33472637, 2021). "Meanwhile, the inflammatory cytokines, such as IL-6, IL-8, and IL-1β can promote tumor proliferation and the occurrence and development of cervical cancer." (PMID 33849528, 2021). "The promotion of IL‐1β and IL‐6 expression of macrophages by poly(I:C)‐treated supernatants was reversed by IL‐6 siRNA interfering in cervical cancer cells." (PMID 31943744, 2020). "poly(I:C)‐stimulated supernatant of cervical cancer cells promoted M1‐type cytokine IL‐1β and IL‐6 expression of THP‐1–derived macrophages, but inhibited the expression of M2‐type cytokine, IL‐10 and CCL22." (PMID 31943744, 2020). "The results showed that the addition of cervical cancer cell supernatant during the differentiation of monocytes into macrophages inhibited the expression of M1 cytokines such as IL‐1β and IL‐6 and promoted M2 cytokines such as IL‐10 and CCL22 expression." (PMID 31943744, 2020). "The objective of this study was to analyze the gene expression profile of the proinflammatory interleukins, (IL-1β and IL-18) in patients with premalignant lesions and cervical cancer." (PMID 31554368, 2019). "According to GEPIA and UALCAN databases, IL‐1B overexpression was observed in cancer tissues and correlated with a shorter survival of cervical cancer patients." (PMID 31222982, 2019). "Other authors have reported a decrease in IL-1β expression in cells derived from cervical carcinoma, SiHa, C4-1, and HPV-infected keratinocytes." (PMID 31554368, 2019). "We investigated mRNA levels of IL‐1B gene and the expression with prognosis in cervical cancer using GEPIA and UALCAN databases." (PMID 31222982, 2019). "IL‐1B mRNA level was up‐regulated in the cervical cancer patients, which was related with poor prognosis in silico." (PMID 31222982, 2019). "GEPIA and UALCAN databases were used to evaluate expression and prognostic of IL‐1B gene in cervical cancer." (PMID 31222982, 2019). "We currently do not know at which time there is a switch from post-translational labilization of pro-IL-1β towards silencing of the gene itself during multi-step progression to cervical cancer." (PMID 23935506, 2013). "Consistent with this notion is also a growth retarding effect on cervical carcinoma cells upon heterotransplantation into nude mice when IL-1β was ectopically expressed." (PMID 23935506, 2013). "While three out of five CIN I lesions still show a positive, but diffuse staining, sections with medium and higher degree of neoplasia (CINII/III lesions) as well as samples from cervical cancer patients gradually lack detectable IL-1β expression." (PMID 23935506, 2013). "Ectopic expression of pro-IL-1β in combination with MG132 treatment or E6-AP siRNA knock-down was able to stabilize pro-IL-1β in cervical carcinoma cells." (PMID 23935506, 2013). "One can therefore propose that there exists a two-step silencing mechanism of IL-1β towards cervical cancer: i) on the post-translational level during immortalization and ii) transcriptionally by gene silencing in malignant cells." (PMID 23935506, 2013).